GPX1 (glutathione peroxidase 1)
Diseases named in the same sentence as GPX1 in open-access papers (continued):
Sharing a sentence is not in itself a finding about the gene and the disease.
chronic obstructive pulmonary disease (4 papers, 2020 to 2024). A chronic and progressive lung disorder characterized by the loss of elasticity of the bronchial tree and the air sacs, destruction of the air sacs wall, thickening of the bronchial wall, and mucous accumulation in the bronchial tree. "An integrative drug safety model explores inhibition of Glutathione Peroxidase 1 by drugs and their association with chronic obstructive pulmonary disease adverse drug events." (PMID 37173537, 2023). "Gpx-1, in particular, has been implicated in chronic obstructive pulmonary disease (COPD) and other inflammatory diseases." (PMID 32008371, 2020). "Statistical and molecular modelling analyses confirmed that the use of several registered drugs, including acetylsalicylic acid and atenolol may be associated with inhibition of Glutathione Peroxidase 1 and chronic obstructive pulmonary disease." (PMID 37173537, 2023). "A GPx1 knockout mouse model of chronic obstructive pulmonary disease (COPD) showed elevated macrophage, neutrophil, interleukin 17 (IL-17) family member, and proteolytic burden in the lungs compared to those of wild-type mice." (PMID 38483584, 2024).
diabetic kidney disease (4 papers, 2008 to 2026). Progressive kidney disorder caused by vascular damage to the glomerular capillaries, in patients with diabetes mellitus. "The presence of oxidative stress in DM_CKD tissue was further supported by our observation of decreased GPX3 levels as well as increased lipid peroxidation in LV tissue, which is consistent with data from mice models of CKD and GPX1 levels in patients with diabetic kidney disease." (PMID 41419687, 2026). "Therefore, the renoprotective role of GPx1 against diabetic kidney disease remains uncertain." (PMID 33477607, 2021).
diabetic neuropathy (4 papers, 2017 to 2025). A chronic, pathological complication associated with diabetes mellitus, where nerve damages are incurred due to diabetic microvascular injury involving small blood vessels that supply these nerves, resulting in peripheral and/or autonomic nerve dysfunction. "In this case–control study, the Pro198Leu polymorphism (rs1050450) in the Gpx1 gene was genotyped in 1244 patients with T2DM (33 % had diabetic neuropathy) and 730 healthy control subjects." (PMID 27592002, 2017). "The mechanism of the observed effect of Gpx1 gene polymorphism on susceptibility to diabetic neuropathy is unknown." (PMID 27592002, 2017). "Notably, glutathione peroxidase 1 (GPX1), a target of interest for diabetic neuropathy induced by oxidative stress, was exclusively expressed in DRG neurons." (PMID 40667173, 2025).
endometriosis (4 papers, 2020 to 2025). The growth of functional endometrial tissue in anatomic sites outside the uterine body. "Moreover, we found significant associations between variant genotypes (CT, TT) of GPX1 198Pro > Leu and the risk of developing endometriosis (p = 0.040 for CT and p = 0.019 for TT)." (PMID 36013572, 2022). "Our study suggested that polymorphisms of GPX1 198Pro > Leu and CAT-262C > T are both associated with the incidence of symptomatic endometriosis." (PMID 36013572, 2022). "Very few articles address the association between aberrant expression of GPX1 and CAT genes and endometriosis." (PMID 36013572, 2022). "Authors suggest that the implication of GPX1 and CAT gene polymorphisms can cause endometriosis but request more extensive studies to confirm their findings." (PMID 36013572, 2022). "Polymorphism of GPX1 198Pro > Leu and CAT-262C > T are both associated with symptomatic endometriosis, and CAT-262C > T and GSTM1 are risk factors for disease’s development." (PMID 36013572, 2022). "Moreover, for the GPX1 198Pro > Leu, the endometriosis group had significantly more frequent CT and TT genotypes." (PMID 36013572, 2022). "This study suggests that GPX1 198Pro > Leu, CAT-262C > T, and GSTM1 polymorphisms may be risk factors and that the association between the GSTM1-GSTT1 null genotype may play a significant role in endometriosis-associated infertility." (PMID 36013572, 2022). "Another enriched pathway across the four conditions is ‘arachidonic acid metabolism’; of the five endometriosis genes enriched in this pathway, four are shared with the other three immune conditions, namely, DPEP3, GPX1, DPEP2, and PON2." (PMID 40262193, 2025). "In contrast, an increase in the ratio of SOD2 over GPx1 corresponds to cell proliferation and metastasis whereas the ratio of SOD2/GPx1 is significantly increased in lesion of ectopic endometriosis." (PMID 37968795, 2024). "This is the first study investigating the association of CAT-262C > T, GPX1 198Pro > Leu, GSTT1, and GSTM1 gene polymorphisms in the Eastern European women population with and without endometriosis, having analyzed a large number of patients." (PMID 36013572, 2022). "Accordingly, the ratio of SOD2/GPx1 was found to be nonsignificantly elevated in the group of endometrial cancer (0.234 ± 0.061) compared with the control group (0.102 ± 0.032) and slightly decreased in the patients of endometriosis (0.0079 ± 0.022)." (PMID 37968795, 2024). "The nonsignificant decrease (P < 0.0001) in GPx1 relative gene expression was observed in the patients with endometriosis compared with the control group (0.351 ± 0.032) and significant increase in GPx1 relative gene levels (0.215 ± 0.043) in the patients with endometrial cancer (0.822 ± 0.111)." (PMID 37968795, 2024).
hyperlipidemia (4 papers, 2018 to 2024). "In our study, the reduced effect of glycine on GPX1 and the increased activities of CAT and Cu/Zn-SOD may be related to enhanced insulin signaling and sensitivity and reduced fat accumulation and hyperlipidemia." (PMID 29675131, 2018).
ischemic stroke (4 papers, 2018 to 2024). A stroke disorder caused by obstruction of blood flow to the brain, due to thrombotic (local blood clot formation) or embolic (due to a blood clot or other material traveling from another site) event. "Allicin protected against astrocyte damage in ischemic stroke by inhibiting inflammation and apoptosis and increasing the expression levels of GPX1." (PMID 37673878, 2023). "Thus, we concluded that allicin significantly prevented and ameliorated ischemic stroke by increasing GPX1 levels to complete the complex physiological process." (PMID 37673878, 2023). "Meanwhile, we found that Ginseng pretreatment significantly enhanced expression levels of Nrf2 downstream cytoprotective and antioxidative proteins including NQO1, HO1, SOD2 and GPx1 at the early stage of ischemic stroke onset in WT, and this was completely abolished in the Nrf2−/− mice." (PMID 29628876, 2018).
lymph node metastases (4 papers, 2018 to 2023). "The presence of lymph node metastasis also significantly associated with decreased GPX1 expression (PADJ = 0.048)." (PMID 30469315, 2018). "Immunohistochemical analysis based on large clinical samples found that high GPX1 expression in oral squamous cell carcinoma is significantly associated with lymph node metastasis, advanced stage, high grade, and invasion and predicts unfavorable patient survival." (PMID 35626163, 2022). "High expression of GPX1 in laryngeal squamous cell carcinoma is significantly correlated with lymph node metastasis and TNM stage (Tumour-Node-Metastasis), which can be applied as a negative prognostic factor for patient survival." (PMID 35626163, 2022).
lymphoma (4 papers, 2019 to 2022). A malignant (clonal) proliferation of B- lymphocytes or T- lymphocytes which involves the lymph nodes, bone marrow and/or extranodal sites. "GPX1 expression is significantly increased in the resistant cells isolated from lymphoma patients with clinical chemoresistance to methotrexate and etoposide." (PMID 35626163, 2022). "With respect to the GSH system, the mRNA level of GR significantly increased, while the mRNA of GPX1 significantly decreased in all lymphoma cells." (PMID 33451071, 2021). "An acylhydrazone heterocycle with GPX1 inhibitory activity has been identified by library screen and crystal structure analysis, which can be used in combination with anticancer drugs to reverse therapy resistance in lymphoma cell lines." (PMID 35626163, 2022). "Seven selenoproteins, that included TXNRD1, GPX1, GPX4, SELENOH, SELENOO, SELENOS and SELENOT, were detected in both lymphoma-derived and primary CD4 T cells." (PMID 35163318, 2022). "Expression of the tumour suppresser gene TXNIP increased, while GPX1 and GPX4 expression, which are related to poor prognosis of lymphoma patients, decreased." (PMID 33451071, 2021). "However, the mRNA level of GPX1 and GPX4 decreased by a different degree in all three lymphomas cell lines." (PMID 33451071, 2021).
Sepsis (4 papers, 2019 to 2024). Sepsis is defined as life-threatening organ dysfunction caused by a dysregulated host response to infection. "Another example is that 593C>T GPx1 SNP in sepsis patients leads to high organ dysfunction, sepsis shock, and mortality risk." (PMID 36419831, 2022). "Although numerous studies have measured GPX1 activity in patients with sepsis, the results remain inconclusive." (PMID 31064391, 2019). "NQO1, GPX-1, and GSTs mRNA levels were enhanced in DJ-1KO hearts compared with WT following CLP-induced sepsis." (PMID 36978809, 2023).
thrombosis (4 papers, 2018 to 2024). "Age-dependent increased susceptibility to venous thrombosis is rescued by overexpression of the antioxidant enzyme GPX-1." (PMID 32168908, 2020). "GPX1 is also involved in the aging process, and its overexpression in aged mice suppresses arterial and venous thrombosis." (PMID 29907735, 2018).
viral infection (4 papers, 2021 to 2022). "In vitro studies have shown that selenium supplementation can inhibit viral infection by increasing glutathione peroxidase 1 (Gpx1) activity and reducing reactive oxygen species (ROS) content, JNK phosphorylation levels." (PMID 36081520, 2022). "Since these mice showed only a small 20 % reduction in GPX1 expression, it is possible that there is a threshold activity of GPX1 and other selenoproteins above which there is little effect on virus infection." (PMID 32758306, 2021). "Overall, these data suggest that GPX1 is important for appropriate cell and tissue responses to a viral infection, in particular in relation to the inflammatory response to respiratory viruses." (PMID 32758306, 2021). "During a viral infection, such as in the case of SARS-CoV-2, the increased production of reactive oxygen species such as hydrogen peroxide is counterbalanced by antioxidants, namely, GPX1, which catalyzes hydrogen peroxide to water." (PMID 34895312, 2021).
acute myeloid leukemia (3 papers, 2016 to 2023). Acute myeloid leukemia (AML) is a group of neoplasms arising from precursor cells committed to the myeloid cell-line differentiation. "In acute myeloid leukaemia patients, high Gpx-1 expression was associated with poor prognosis." (PMID 37242524, 2023). "The purpose of the study was to evaluate the association between CAT C262T, GPX1 Pro198Leu, MnSOD Ala16Val, GSTM1, GSTT1, and GSTP1 Ile105Val gene polymorphisms and acute myeloid leukemia risk, in a case-control study comprising 102 patients and 303 controls." (PMID 26823947, 2016). "According to the prediction from The Cancer Genome Atlas (TCGA) database, we discovered that glutathione peroxidase 1 (GPX1) was up-regulated in acute myeloid leukemia (LAML) tissues, which pushed us to explore the feasible role and its related modulatory mechanism of GPX1 in ALL." (PMID 32808668, 2020).
alcohol (3 papers, 2021 to 2024). "The gene expression changes of superoxide dismutase 2 (SOD2) and glutathione peroxidase 1 (Gpx1) related to acute alcohol liver injury were investigated at 3 h after alcohol injection." (PMID 34959956, 2021). "Also in a prior study, supplementation with BCAAs in-creased the mRNA levels of glutathione peroxidase 1 (GPX1), catalase, and SOD in the liver tissue of alcohol-induced rats." (PMID 38111317, 2024).
autism spectrum disorder (3 papers, 2012 to 2023). A spectrum of developmental disorders that includes autism, and Asperger syndrome. "Further, a common genetic variant of GPX1 was found to be under transmitted from parents to children with autism spectrum disorder, suggesting a protective effect of a wild-type GPX1." (PMID 36969558, 2023).
Cognitive impairment (3 papers, 2021 to 2025). Abnormal cognition is characterized by deficits in thinking, reasoning, or remembering. "We show that cognitive impairment is associated with elevated levels of protein carbonylation and lipid peroxidation as well as down-regulated Gpx1 expression in the hippocampus of CS exposed and CS cessation mice." (PMID 35351173, 2022).
Crohn disease (3 papers, 2017 to 2024). A gastrointestinal disorder characterized by chronic inflammation involving all layers of the intestinal wall, noncaseating granulomas affecting the intestinal wall and regional lymph nodes, and transmural fibrosis. "Genotypic frequencies and overall association of genetic variants in SOD2 and GPX1 with Crohn’s disease and ulcerative colitis." (PMID 28052094, 2017). "Association of SNPs in the antioxidant system genes SOD2 and GPX1 with Crohn’s disease clinical characteristics." (PMID 28052094, 2017). "Single nucleotide polymorphisms (SNPs) in the antioxidant genes SOD2 (rs4880) and GPX1 (rs1050450) were genotyped in a Portuguese population comprising 436 Crohn’s disease and 367 ulcerative colitis patients, and 434 healthy controls." (PMID 28052094, 2017).
dementia (3 papers, 2011 to 2020). Loss of intellectual abilities interfering with an individual's social and occupational functions. "However, a case–controlled study on the association of GPx‐1 and GPx4 polymorphisms with episodic memory and AD in southern Brazil found that TT homozygotes showed a lower score for long‐term visual memory, but could be related to lower risk for dementia." (PMID 33070477, 2020).
end-stage renal disease (3 papers, 2016 to 2019). "We assessed the association between polymorphisms in Nrf2, superoxide dismutase (SOD2), glutathione peroxidase (GPX1), and the risk of end-stage renal disease (ESRD)." (PMID 31340563, 2019). "It is important to note that polymorphic expression of either SOD2 and/or GPX1 influences susceptibility to end-stage renal disease (ESRD) and transitional cell carcinoma (TCC), both associated with BEN progression and complications." (PMID 31382611, 2019). "The polymorphisms in Nrf2, superoxide dismutase (SOD2), and glutathione peroxidase (GPX1) genes, individually, have been implicated previously in disease susceptibility or prognosis in end-stage renal disease (ESRD), CKD, or diabetic nephropathy patients." (PMID 31340563, 2019). "We prospectively enrolled multicenter patients with end-stage renal disease (ESRD) and those without chronic kidney disease (CKD) of Han Chinese origin, with SOD2 (Val16Ala), GPX1 (Pro197Leu), and PPAR-γ (Pro12Ala, C161T) genotyped." (PMID 26881045, 2016).
endometrial cancer (3 papers, 2017 to 2024). Primary or metastatic malignant neoplasm involving the endometrium (mucous membrane that lines the endometrial cavity). "In the literature review, no analyses were found regarding the relationship between the polymorphisms GPX1 (rs1050450), DIO2 (rs225014) and SEPP1 (rs7579) and the possibility of developing endometrial cancer." (PMID 35205233, 2022). "Our study attempted to determine whether polymorphisms in selected genes important for selenium metabolism, GPX1 (rs1050450), DIO2 (rs225014) and SEPP1 (rs7579), are associated with the risk of developing endometrial cancer." (PMID 35205233, 2022). "Based on this study and our study on endometrial cancer, we recommend follow-up of interactions between acrylamide intake and SNPs for ovarian and endometrial cancer risk, particularly SNPs in CYP2E1, GSTs, the HSD3B1/B2 gene cluster, AKR1C1, NQO1, GPX1 and MGC12965." (PMID 28391539, 2017).
gastric adenocarcinoma (3 papers, 2013 to 2017). "In this study, we immunohistochemically examined the expressions of GPX1, CDX2, and Ki67 in 172 samples of human gastric adenocarcinomas." (PMID 24228025, 2013).
hearing loss (3 papers, 2019 to 2024). "The targeted mutation of the GPx1 gene in mice also increased their vulnerability to noise-induced hearing loss." (PMID 31680814, 2019). "In accordance with our study, a decrease in GPx1 activity was shown to play an important role in noise-induced hearing loss." (PMID 31680814, 2019). "In the auditory system, a previous study reported that a single nucleotide polymorphism in GPX1 might be associated with the vulnerability to noise-induced hearing loss (NIHL) among the Chinese Han population." (PMID 35401119, 2022). "Our finding is consistent with previous studies indicated that a decrease of GPX1 activity was found in mouse cochlea HCs and stria vascular after noise induced hearing loss, and suggested that the antioxidant enzyme GPX1 might play a role in the oxidative injury of SGNs induced by peroxynitrite." (PMID 35401119, 2022). "Furthermore, several mouse lines, which were deficient for antioxidant components, such as superoxide dismutase 1 (SOD1), glutathione peroxidase 1(GPX1), plasma membrane calcium ATPase 2(PMCA2) or Cadherin Related 23 (CDH23) showed also increased sensitivity to noise-induced hearing loss." (PMID 38397817, 2024).
hyperthyroidism (3 papers, 2014 to 2025). Overactivity of the thyroid gland resulting in overproduction of thyroid hormone and increased metabolic rate. "Co-administration of vitamin E and curcumin improved the activities of enzymatic antioxidant including cytosolic catalase, cytosolic glutathione peroxidase-1 (GPx1), mitochondrial SOD2 and glutathione reductase, and normalized GPx1 protein expression in l-thyroxine-induced hyperthyroidism in rat." (PMID 24674233, 2014). "The increase in ROS production mediated by hyperthyroidism was correlated with an increase in the genomic expression of the antioxidant enzymes CAT and GPx-1 in lymphoid cells of lymph nodes and spleen, evaluated by conventional PCR and real-time PCR." (PMID 31281590, 2019).
Infertility (3 papers, 2022 to 2025). "In the context of comparisons between fertile and infertile men, the present study represents the only report investigating the concentrations of the enzymes SOD, GPX, and NOS in seminal plasma, specifically focusing on their individual isoforms (SOD1, GPX1, and NOS1)." (PMID 41462670, 2025).
injury (3 papers, 2020 to 2024). Damage inflicted on the body as the direct or indirect result of an external force, with or without disruption of structural continuity. "Although the association between CCL2 and these two antioxidant-related genes is unknown, C-C motif chemokine ligand 5, a member of the same chemokine family, has been shown to enhance glutathione peroxidase 1 antioxidant activity in mice with mild traumatic brain injury." (PMID 36992978, 2023).
kidney cancer (3 papers, 2019 to 2023). Primary or metastatic malignant neoplasm involving the kidney. "Similarly, kidney cancer studies from Gumz and Yusenko confirmed that GPX1 was expressed higher in ccRCC tissues than that in adjacent normal tissues." (PMID 31844035, 2019).
liver cancer (3 papers, 2013 to 2024). An epithelial or non-epithelial malignant neoplasm that arises from the liver. "A study revealed that notopterol downregulated the expression levels of p-JAK2, ATF4, glutathione peroxidase 1 (GPX1), catalase (CAT), and superoxide dismutase 1(SOD1) proteins in liver cancer cell lines, thereby reducing the proliferation and invasion capabilities of cancer cells." (PMID 39770441, 2024). "The reduction of SBP1 increased cell migration and GPX1 activity, and the combination of decreased SBP1 and enhanced GPX1 activity could be observed in liver cancer patients with macrovascular invasion." (PMID 23567478, 2013).